WBP2 (WW domain binding protein 2)
Diseases named in the same sentence as WBP2 in open-access papers (continued):
Sharing a sentence is not in itself a finding about the gene and the disease.
breast carcinoma (continued). "WBP2 inhibited the metformin response of HER2+ breast cancer in vitro and in vivo." (PMID 41744824, 2026). "In breast cancer tissues, the knockdown of WBP2 inhibits cell proliferation and promotes apoptosis." (PMID 38239300, 2024). "WBP2 promotes carcinogenesis in breast cancer by regulating important cellular pathways." (PMID 38473318, 2024). "Given that WBP2 upregulation was observed at higher breast cancer stages via immunohistochemistry analysis, we speculated that WBP2 protein expression in TCGA BRCA samples can be similarly associated with breast cancer stage progression." (PMID 34197030, 2022). "With consideration of the tumor‐promoting role of BTRC, and the positive regulatory role of WBP2 on BTRC, we questioned whether WBP2 mediates breast cancer migration and invasion via BTRC." (PMID 34197030, 2022). "Besides breast cancer, WBP2 has been reported to play an oncogenic role in multiple cancer types such as skin, brain, liver, lung, and gastric cancers." (PMID 34197030, 2022). "WBP2 is a multifunctional protein that has mainly been studied in the context of breast cancer." (PMID 34724825, 2021). "Besides breast cancer, WBP2 overexpression has also been observed in tumours of the liver, stomach, lung and skin, compared to adjacent normal tissues, through IHC experiments." (PMID 34831354, 2021). "WW domain binding protein-2 (WBP2) can function as a Yes-associated protein/transcriptional co-activator with PDZ-binding motif (YAP/TAZ) co-activator and has a crucial role in promoting breast cancer progression." (PMID 33837178, 2021). "Functionally, WBP2 has been found to promote several cancer phenotypes including growth, cell cycle progression, migration, invasion, epithelial mesenchymal transition and chemotherapeutic resistance in a number of breast cancer cell lines." (PMID 34831354, 2021). "Together with the clinical bioinformatics analyses, these findings indicated that WBP2 could impose its oncogenic functions by inhibiting the tumor-suppressive properties of the microprocessor complex in breast cancer." (PMID 34117091, 2021). "With prior knowledge that metformin may inhibit YAP nuclear translocation through the promotion AMPK-induced AMOT stabilization, we postulate that WBP2 can be used as a combinatorial therapy with metformin in HER2+ breast cancer." (PMID 34831354, 2021). "Studying the WBP2/microprocessor complex in other breast cancer cell lines such as BT-474 could enlighten the constant interacting partner of WBP2 in the complex." (PMID 34117091, 2021). "The reregulation of miRNA biogenesis machinery via targeting WBP2 protein may have implications in breast cancer therapy." (PMID 34117091, 2021). "Furthermore, an analysis of WBP2 protein-mRNA correlation over a panel of 17 breast cancer cell lines revealed only a partial concordance of approximately 50%." (PMID 34831354, 2021). "This suggests that WBP2 is a prognostic marker in HER2+ breast cancer." (PMID 34831354, 2021). "Therefore, reducing WBP2 expression in clinical breast cancer patients is likely to improve patients’ response towards these anti-cancer drugs." (PMID 34831354, 2021). "The first evidence of WBP2 as a potential oncogene in breast cancer was observed by our laboratory." (PMID 34831354, 2021). "Hence, the expression profiles of WBP2 and miR-23a in breast cancer samples were analyzed using cBioPortal database." (PMID 32820148, 2020). "Collectively, the in vitro and in silico data support the notion that the MST1/2 → miR-23a → WBP2 could have a clinical significance in breast cancer." (PMID 32820148, 2020). "Moreover, TCGA meta-analysis showed a downregulation of miR-23a in breast invasive carcinoma samples, reflecting that WBP2 oncogene is regulated by a potential tumor suppressor miR-23a in breast cancer." (PMID 32820148, 2020). "Finally, nuclear WBP2 levels correlated inversely with disease-free and overall survival of breast cancer patients." (PMID 32393834, 2020).
breast carcinoma (continued). "Moreover, miR-206 overexpression and WBP2 knockdown reduced tamoxifen-resistance in breast cancer cells." (PMID 31590453, 2019). "Our finding provides a new mechanism for the chemotherapy response of ERα-positive breast tumours, and WBP2 might be a key molecule for developing new therapeutic strategies to treat chemoresistance in breast cancer patients." (PMID 29937544, 2018). "Similarly, breast cancer tissue with high expression of WBP2 showed higher expression of MDR1 than breast samples with low WBP2 expression." (PMID 29937544, 2018). "Our findings provide a novel mechanism of ERα-mediated chemoresistance and suggest that WBP2 might be an effective target for the development of novel therapeutic strategies to overcome multiple drug resistance in breast cancer." (PMID 29937544, 2018). "WBP2 has been reported to play a critical role in promoting cell metastasis in breast cancer cells." (PMID 29497031, 2018). "WW domain-binding protein 2 (WBP2) has been demonstrated as oncogenic in breast cancer." (PMID 29497031, 2018). "Besides, WBP2 was positively correlated with ER (ESR1) expression in 3762 ER+ breast cancer patients utilising Breast Cancer Gene Expression Miner v4.1." (PMID 29937544, 2018). "WBP2 tyrosine phosphorylation could enhance the transcription of estrogen receptor α, which induced the angiogenesis of breast cancer." (PMID 30001383, 2018). "Thus, our findings confirm that WBP2 upregulation also enhanced the resistance effect of doxorubicin in nude mice bearing breast cancer tumours." (PMID 29937544, 2018). "To obtain more supporting evidence to validate our findings, we analysed the correlation between MDR1 and WBP2 using TCGA data set, which contained 1090 breast cancer patients and result showed that there was a slight positive relativity between MDR1 (ABCB1) and WBP2 (p = 0.050)." (PMID 29937544, 2018). "Besides ER, a number of other nuclear hormone receptors and transcriptional factors in the cells contain WW domain and WBP2 possibly interacts with these molecules to activate cancer-promoting genes in breast cancer." (PMID 28724435, 2017). "In addition, studies show that phosphorylated WWOX is able to physically bind to the PPxY motif of WBP2 and inhibit the ER transactivation pathway, further attenuating the process of breast cancer." (PMID 28724435, 2017). "Exploration of the other functions of WBP2 may provide more clues to the vital role of WBP2 in the development and progress of breast cancer." (PMID 28724435, 2017). "Additionally, a survey of public microarray data repositories for survival among 5667 breast cancer patients in KM plotter database demonstrated that elevated WBP2/BTRC/IκBα gene signature is significantly correlated to distant metastasis‐free survival (DMFS) with a hazard ratio (HR) of 1.37." (PMID 34197030, 2022). "Moreover, the level of WBP2 protein in normal mammary epithelial and breast cancer cell lines could be elevated with the treatment of proteasomal inhibitors or silencing of ITCH E3 ligase." (PMID 32393834, 2020). "Studies have shown that in the breast cancer cell line MDA-MB-231, WBP2 initiates cellular Wnt activity through the upregulation of GPS1 and TNIK." (PMID 38289496, 2024). "Given that WBP2 promotes BTRC expression, we investigated their coexpression in a breast cancer cell line panel." (PMID 34197030, 2022). "In mammalian systems, the binding between WBP2 and YAP confers proliferative advantage in normal and malignant epidermal stem cells, as well as in breast cancer." (PMID 34831354, 2021). "The first hint of a potential role of WBP2 in Wnt pathway was the observations that WBP2 overexpression stabilized β-catenin and activated TCF reporter activity in breast cancer cells." (PMID 32393834, 2020). "More high-resolution research on WBP2 and chromatin remodeling will be needed in order to exploit HDAC inhibitors for targeted therapeutics of WBP2-positive breast cancer." (PMID 32393834, 2020).
breast carcinoma (continued). "Next, we analyzed the protein expression of MST1, MST2, and WBP2 in a panel of breast cancer cell lines to determine the correlation between MST and WBP2 expression." (PMID 32820148, 2020). "The use of PDXs was of fundamental importance to define the role of WW-binding protein 2 (WBP2), an oncogenic coactivator, co-amplified with HER2 in 36% of HER2-positive breast cancers." (PMID 32210163, 2020). "Breast cancer cells co-expressing MST1-K59R and WBP2 significantly decreased the overall survival of the animals compared to those expressing MST1-K59R alone supporting WBP2 and MST as prognostic factors." (PMID 32820148, 2020). "In the present study, we posit that ERα interacts with WBP2 to enhance the transcriptional level of MDR1, resulting in chemoresistance of breast cancer cells by increasing membrane drug pump function." (PMID 29937544, 2018). "Herein, we evaluated the expression levels of WBP2 in human normal breast epithelial cells MCF10A and several types of breast cancer cells." (PMID 29937544, 2018). "However, FH535, a Wnt/beta-catenin inhibitor, blocks phospho-WBP2-induced tumorigenesis more dramatically than tamoxifen, in part by decreasing ERα level, suggesting tyrosine phosphorylation of WBP2 regulates ERα function in breast cancer partly via the Wnt pathway." (PMID 28724435, 2017). "Analysis of HER2-positive breast cancer samples supports the negative correlation between WBP2 expression and activated AMPK observed in vitro." (PMID 41744824, 2026). "Notably, WBP2, a gene co-expressed at position 68 of GPS1, is an emerging oncogene that has received recent attention for its oncogenic role in TNBC breast cancers." (PMID 38289496, 2024). "Although the expression of WBP2 in adenomyosis tissue has not been reported, its expression and function in hepatocellular carcinoma and breast cancer have been confirmed." (PMID 38239300, 2024). "Together, these in vitro findings led us to the hypothesis that elevated WBP2 and BTRC expression, coupled with reduced IκBα expression, predicts poorer prognosis for clinical breast cancer." (PMID 34197030, 2022). "Our group has previously reported that WBP2 can activate JNK pathway in breast cancer; however, the involvement of WBP2 in NF‐κB signaling has not been explored." (PMID 34197030, 2022). "Taken together, WBP2 potentially regulates microprocessor complex activity in a negative fashion in both breast cancer cells." (PMID 34117091, 2021). "Clinically, the importance of these WBP2-targeting miRNAs is supported by meta-analysis which revealed a considerable downregulation of miR-206 and miR-485 in breast cancer with a corresponding negative correlation with WBP2 expression." (PMID 32393834, 2020). "Furthermore, western blotting was conducted to determine the protein levels of WBP2 and MDR1 in human breast cancer tissues." (PMID 29937544, 2018). "This indicated that WBP2-mediated doxorubicin resistance of breast carcinoma in vivo was independent of body weight changes." (PMID 29937544, 2018). "Additionally, RNA level of WBP2 is decreased in the MCF10AT model, which mimics the different stages of progression of breast cancer in a series of isogenic, xenograft-derived cell lines." (PMID 28724435, 2017). "Thus, both WBP2 and WBP2NL genes are highly related to the angiogenesis of breast carcinoma through the modulation of EGF, ER, and other downstream signaling proteins." (PMID 28724435, 2017). "Hence, we evaluated whether WBP2, a HER2-coamplified gene, can regulate the response of HER2+ breast cancer to metformin." (PMID 41744824, 2026). "Additionally, WBP2 (WW domain-binding protein 2) is an emerging oncogene involved in Wnt, EGFR, Hippo, and PI3K /Akt pathways.It was reported that inhibition of WBP2 expression by miR-613 repressed breast cancer growth." (PMID 39698025, 2023).
breast carcinoma (continued). "The antagonistic effect of MST and Dicer on WBP2 was demonstrated in the majority of the breast cancer cell lines tested including the TNBC and validated in xenograft models, supporting the notion that MST acts as yet another rheostat that regulates the expression of WBP2." (PMID 32820148, 2020). "The relationship between inflammation and cancer is established and studies show that WBP2 expression can enhance the proliferation and metastatic ability of breast cancer cells; however, to our knowledge, the expression and function of WBP2 in glioma has not been reported." (PMID 29497031, 2018). "Therefore, our results indicate that WBP2 expression is highly correlated with MDR1 expression in chemotherapy treatment breast cancer patients, and WBP2, ER and MDR1 gene signature might be served as a predictive marker for resistant to chemotherapy in breast cancer patients." (PMID 29937544, 2018). "Although WBP2 did not regulate the expression level of the microprocessor complex components, that is, DGCR8, Drosha, DDX5, and DDX17, it suppressed the activity of pri-miRNA–processing machinery via physical interactions with these components in breast cancer." (PMID 34117091, 2021).
glioma (9 papers, 2017 to 2023). A benign or malignant brain and spinal cord tumor that arises from glial cells (astrocytes, oligodendrocytes, ependymal cells). "These include hepatocellular carcinoma, non-small cell lung cancer, glioma and gastric cancer, where WBP2 has already been reported to be functionally implicated." (PMID 34831354, 2021). "This study aimed to illustrate the underlying mechanism by which WBP2 regulates the process of glioma development." (PMID 29497031, 2018). "Many studies have revealed the WBP2 gene as a high-risk gene for leukoariaosis and cerebral white matter lesions is important in the pathologic stage of glioma development." (PMID 29497031, 2018). "Furthermore, WBP2 status was positively associated with higher pathological stages and poorer survival in human glioma, gastric and non-small cell lung carcinoma (NSCLC) patients." (PMID 34831354, 2021). "In glioma cells, WBP2 regulates α enolase-mediated glycolysis to aggravate cell proliferation and migration." (PMID 34831354, 2021). "In a study performed in glioma cells, WBP2 was found to induce the Akt pathway through its interaction with the α-enolase (ENO1) glycolytic enzyme." (PMID 34831354, 2021). "Cancers with high WBP2 mRNA levels such as glioma, melanoma, and thyroid had low protein expression level, whereas pancreatic and colorectal cancers with a high WBP2 protein level display low mRNA expression." (PMID 32393834, 2020). "Elevated WBP2 expression has also been reported in human gliomas and exogenous WBP2 increased cell proliferation, migration, and cell cycle progression." (PMID 32393834, 2020). "Compared with the EGFP-Vector control group, WBP2 overexpression obviously promoted glucose consumption and lactate formation in glioma cells (left two bars)." (PMID 29497031, 2018). "Overexpression of WBP2 in glioma cells promoted cell proliferation and migration, and the number of S-phase cells, whereas the depletion of WBP2 by RNAi-mediated knockdown restrained cell growth and cell cycle progression." (PMID 29497031, 2018). "To verify the expression pattern of WBP2 in glioma, we performed immunohistochemical (IHC) staining with WBP2 antibody to evaluate WBP2 protein levels, using tissue microarray." (PMID 29497031, 2018). "We ablated the expression of WBP2 using RNAi-mediated knockdown in U251 and U87 cells to better interpret the role of WBP2 in the development of glioma." (PMID 29497031, 2018). "Their interaction is probably part of the mechanism by which WBP2 regulates the proliferation and migration of glioma cells." (PMID 29497031, 2018). "We not only discovered that upregulation of WBP2 accelerated glucose uptake rate, but that it also enhanced the secretion speed of lactate in glioma cell lines and the tumor mass of mice." (PMID 29497031, 2018). "Our research illustrated a relationship between WBP2 and glycolysis enzyme activity in tumor cells and revealed a novel potential regulatory mechanism in glioma progression." (PMID 29497031, 2018). "To determine the underlying molecular mechanisms by which WBP2 regulates glioma cell properties, we examined the protein partners of human WBP2 in glioma cells by affinity adsorption using the plasmid pGEX-4T-1-GST-WBP2." (PMID 29497031, 2018). "To investigate possible influencing factors in WBP2-mediated enhancement of glioma cell growth, we analyzed the cell cycle profile in WBP2-overexpressed and WBP2-knockdown cells by flow cytometry." (PMID 29497031, 2018). "Collectively, these results reveal that WBP2 plays a vital role in the occurrence and development of glioma, indicating a target gene for glioblastoma treatment." (PMID 29497031, 2018). "In the present study, we discovered a high expression of WBP2 in several tumor cell lines and glioma tissue chip." (PMID 29497031, 2018). "We also found that overexpression of WBP2 enhanced, while downregulation of WBP2 expression suppressed, the proliferation, migration, and tumor formation ability of Glioma cells." (PMID 29497031, 2018).